NAT10 (N-acetyltransferase 10)
Diseases named in the same sentence as NAT10 in open-access papers (continued):
Sharing a sentence is not in itself a finding about the gene and the disease.
tumor (continued). "Future extensive research on NAT10's role in tumor multidrug resistance mechanisms could lead to the development of new drugs targeting NAT10, expanding treatment options for drug‐resistant cancers." (PMID 39764566, 2025). "Second, NAT10's role within tumor cells will also be of interest." (PMID 39764566, 2025). "The importance of NAT10 in regulating the tumor cell cycle has garnered increasing attention." (PMID 39764566, 2025). "This suggests that NAT10 may serve as an important biomarker for evaluating tumor progression and treatment response." (PMID 39764566, 2025). "NAT10 promotes tumor metastasis by enhancing ac4C-dependent GLMP mRNA stability." (PMID 41446042, 2025). "Therefore, in‐depth research on the mechanisms of NAT10‐mediated ac4C acetylation in tumor metabolism can help reveal new aspects of tumor metabolic regulation and provide new targets and strategies for cancer treatment." (PMID 39764566, 2025). "We noticed that NAT10 could affect tumour-related signalling pathways by analysis of the sequencing data." (PMID 40169553, 2025). "Further investigation into the role of NAT10 in tumor biology could enable more precise prognostic assessments for patients and help optimize therapeutic strategies, ultimately improving clinical outcomes." (PMID 39764566, 2025). "By regulating these checkpoints, NAT10 may affect the response of tumor cells to DNA damage or other stress factors, influencing cancer cell stress responses and drug resistance." (PMID 39764566, 2025). "Notably, NAT10‐2023 treatment resulted in a substantially higher rate of anoikis compared to apoptosis, further highlighting its efficacy in disrupting tumor cell adhesion." (PMID 41476650, 2025). "However, NAT10 levels are positively correlated with E‐cadherin levels in CRC, potentially suggesting a discrepant regulatory effect of NAT10 on E‐cadherin in different tumor types." (PMID 39817252, 2025). "Additionally, increased NAT10 expression promotes glycolysis in tumor cells by stabilizing YTHDC1, PFKM, and LDHA mRNA, thus providing essential energy support for tumor growth." (PMID 39897026, 2025). "Moreover, the NAT10 inhibitor in combination with olaparib exerted a synergistic anti-tumor effect by accelerating the accumulation of DSBs in vivo and in vitro." (PMID 40606759, 2025). "In addition to suppressing immune cell function, NAT10 further drives tumor progression by recruiting and polarizing M2 macrophages." (PMID 41316475, 2025). "Our findings suggest that the depletion of NAT10-mediated ac4C modification, including using NAT10 inhibitors include Rem, could significantly reduce tumor progression when combined with other small-molecular inhibitors or FDA-approved drugs." (PMID 40119353, 2025). "Further analysis revealed that NAT10 inhibition, in combination with PD-L1 blockade, exhibited a synergistic antitumor effect, offering a promising therapeutic strategy to overcome the immunosuppressive tumor microenvironment (TME) in PC." (PMID 41203621, 2025). "In conclusion, NAT10 knockdown retarded tumor growth in the mouse model." (PMID 40344913, 2025). "Additionally, immunohistochemical (IHC) analysis of HCC tissue microarrays (TMA) revealed that NAT10 expression was significantly upregulated in 95 tumor tissues compared to 87 adjacent non‐tumor tissues from HCC specimens." (PMID 41476650, 2025). "Furthermore, NAT10 can impact tumor progression by targeting oncogenes and proteins, implicating NAT10 as a potential target for the diagnosis and treatment of a variety of cancer types." (PMID 39817252, 2025). "NAT10 mediates ac4C acetylation, playing a crucial role in tumor progression." (PMID 39764566, 2025). "Additionally, NAT10 depletion significantly impairs tumor growth, metastasis, and hepatocarcinogenesis in vivo." (PMID 41476650, 2025).
tumor (continued). "NAT10 promotes tumor progression in an ac4C-dependent manner in various solid tumors." (PMID 40119353, 2025). "In melanoma, NAT10 silencing induces S-phase cell cycle arrest by downregulating Microphthalmia-associated Transcription Factor (MITF) expression, significantly suppressing tumor cell proliferation in both in vitro and in vivo experimental systems." (PMID 40881352, 2025). "Tumor tissues had higher NAT10 expression levels than those of non-tumor tissues." (PMID 39905540, 2025). "Therefore, NAT10 can regulate the expression levels of target oncogenes via acetylation modification, which can ultimately affect tumor cell proliferation, metastasis, and invasion." (PMID 39817252, 2025). "To further explore the association between NAT10 expression and liver metastasis in GC, we performed immunohistochemical (IHC) staining on a tissue microarray (TMA) containing 75 primary tumor samples (cohort 1) from GC patients with liver metastasis (n = 23) or without liver metastasis (n = 52)." (PMID 39985269, 2025). "Compared with the control group, the NAT10 knockdown group showed a significant inhibition in the growth of tumours, and the group treated with the NAT10 inhibitor Remodelin also showed a significant inhibition in the growth of tumours." (PMID 40169553, 2025). "NAT10 promoted tumor cell migration and malignant transformation." (PMID 38308713, 2024). "NAT10 is involved in multiple cancers and performs a tumor-promoting function." (PMID 38243170, 2024). "Interestingly, small molecule compounds targeting NAT10 K823Khib have recently been developed for anti-tumor metastasis." (PMID 38308713, 2024). "Knockdown of NAT10 significantly reduced the tumor volume and weight in the mouse xenograft model." (PMID 39085201, 2024). "In addition, it was observed that inhibiting the NAT10 expression with Remodelin, in combination with antiangiogenic therapy (Apatinib), successfully decreased tumor progression in in vivo and in vitro." (PMID 39640362, 2024). "Moreover, it is of great significance to consider CLIC3 expression in tumor when targeting NAT10 for therapeutic purposes." (PMID 38182571, 2024). "Therefore, RNA ac4C and NAT10 have the potential to serve as effective biomarkers for tumor diagnosis, poor prognosis, and clinical therapeutic targets." (PMID 38308713, 2024). "Development of small molecule inhibitors directly targeting NAT10 or impeding NAT10-THUMPD1 interaction could be a good strategy for tumor therapy." (PMID 38308713, 2024). "Secondly, according to the current research, transcription factor (TF) could activate the transcription of gene and thus promote the expression level of gene in tumours, which provides some insights into the upregulation of NAT10 in DLBCL." (PMID 38961519, 2024). "Additionally, NAT10 was shown to inhibit CD8+ T cell accumulation near the tumor via the CCL25/CCR9 axis, fostering an immunosuppressive microenvironment." (PMID 39648231, 2024). "Therefore, NAT10 is an oncogenic protein with carcinogenic properties and can be used as a biomarker for tumor diagnosis." (PMID 38308713, 2024). "In vivo experiments showed that knockdown of NAT10 markedly suppressed tumor growth." (PMID 38243170, 2024). "Given the interaction between RNPS1 and NAT10 and the existing research indicating NAT10’s impact on tumor occurrence and progression in various cancers, we aimed to investigate whether RNPS1 affects the advancement and metastasis of HNSCC." (PMID 38246918, 2024). "The effects of NAT10 on immune microenvironment and tumor metabolism were investigated." (PMID 39363363, 2024).
tumor (continued). "Consequently, NAT10 expression in tumor tissues was scored by the intensity of staining in the nucleus." (PMID 38243170, 2024). "The role of NAT10‐mediated ac4C in various tumor progression is also summarized." (PMID 39640362, 2024). "But the role of NAT10 in tumor immunity remains unexplored and undocumented." (PMID 38243170, 2024). "The mechanism is that NAT10 catalyzes the formation of ac4C modification in mRNA, maintains mRNA stability and improves translation efficiency, thereby increasing gene expression and thus promoting tumor formation." (PMID 38233930, 2024). "Results demonstrated a strong correlation between NAT10 and mRNAsi, indicating that NAT10 may play a role in modulating tumor stem cell behavior." (PMID 39648231, 2024). "NAT10 was originally found to regulate telomerase activity and rRNA transcription in the nucleolus, thus playing a role in delaying aging, preventing osteoporosis and promoting tumor metastasis." (PMID 37612540, 2023). "Current studies suggest that NAT10-mediated RNA ac4C modification is involved in the pathophysiology of various diseases, including viral replication and stability 39,40, spermatogenesis 41, and tumor progression 42,43,44." (PMID 37484809, 2023). "Moreover, to investigate the potential synergistic enhancement of anti‐PD‐L1 efficacy through combination treatment with NAT10 knockdown, we also monitored tumor growth after anti‐PD‐L1 antibody treatment in different groups in the model." (PMID 37818745, 2023). "In vivo study, the subcutaneous tumor-forming assay was used in nude mice to detect the changes in the subcutaneous tumor-forming ability of HCC cells after NAT10 inhibition, and the changes in metastasis ability of HCC cells and the efficacy of lenvatinib after NAT10 downregulation." (PMID 36765042, 2023). "This may be another novel mechanism by which NAT10-mediated ac4C modification is involved in tumor progression." (PMID 37484809, 2023). "NAT10 has been reported to delay aging, prevent osteoporosis and promote tumor metastasis." (PMID 36765042, 2023). "We further explored the biological significance of MDM2 in the tumor-promoting function of NAT10." (PMID 36609449, 2023). "LINC00623 is able to bind to N-acetyltransferase 10 (NAT10) and recruit USP39, which prevents NAT10 from ubiquitin-mediated degradation, thereby promoting tumor progression by stabilizing the downstream oncogenic mRNAs through mediating the N4-acetylcytidine modification." (PMID 38174069, 2023). "Therefore, further elucidation of the comprehensive molecular mechanisms of NAT10-mediated mRNA acetylation modification is of great significance for understanding the role of that new mRNA modification in tumor spread." (PMID 37914704, 2023). "Since hypoxia is a common feature of solid tumors, the correlation between HIF‐1α and NAT10 may provide a clear explanation for the substantial enrichment of NAT10 in multiple tumor tissues." (PMID 37328448, 2023). "Our findings reveal the tumor-promoting role of NAT10-mediated FOXM1 upregulation in LSCC, which may help to discover novel diagnostic or therapeutic targets for LSCC patients." (PMID 37948132, 2023). "To narrow down the gene list and search for the prognostication-relevant genes that were associated with NAT10, we conducted univariate analysis using Cox proportional hazard regression model in PDAC cases with sufficient tumor purity (n = 56), taking into account both PFS and OS." (PMID 36949954, 2023). "Impressively, NAT10 knockdown acted synergistically with PD‐L1 blockade therapy in vivo, leading to tumor regression by impairing tumor cell glycolysis, decreasing lactic acid production, attenuating immunosuppression and improving immunosurveillance (as shown in the Graphical Abstract)." (PMID 37818745, 2023). "In addition, IHC analysis of tumor tissues in four groups showed that silencing of NAT10 led to the downregulated ki67 expression, while the ki67 expression was enhanced again after overexpression of FOXM1." (PMID 37948132, 2023).
tumor (continued). "The expression of the NAT10 gene in in tumor and normal tissues, and the results are shown in." (PMID 36949954, 2023). "Moreover, HOXC8 facilitated NAT10 transcription in CCa cells by binding to its promoter region, which facilitated the proliferation, migration and invasion of CCa cells in vitro and tumor progression in vivo." (PMID 37818745, 2023). "According to our acRIP-sequencing (acRIP-seq) assay, NAT10-mediated ac4C modification may promote HNSCC tumor progression by regulating the MAPK pathway." (PMID 37914704, 2023). "Collectively, these data underscore the oncogenic function of upregulated FOXP1 in CCa malignant progression; thus, FOXP1 upregulation could ameliorate the tumor‐suppressive effect of NAT10 depletion in CCa cells." (PMID 37818745, 2023). "Consistent with the in vivo results, the results in this model confirmed that overexpression of FOXP1 can attenuate the suppressive effect of NAT10 knockdown on tumor growth in vivo, further emphasizing the crucial role of ac4C modification catalyzed by NAT10 in CCa tumor development." (PMID 37818745, 2023). "Reports have elucidated the importance of NAT10 in tumor progression." (PMID 37948132, 2023). "Thus, we observed that the tumor tissues showed higher NAT10 expression levels, consistent with TCGA and GEO datasets (GSE41258)." (PMID 36522719, 2022). "Similarly, re‐expressed SOX4 rescued the effects of reduced tumour‐sphere formation capacity after the suppression of NAT10." (PMID 35522942, 2022). "Compared with the wild‐type mice, NAT10‐cKO mice carried a lower tumour burden." (PMID 35522942, 2022). "Additionally, we found a significant decrease in NAT10 and Ki67 (proliferation marker protein) levels and a significant increase in Caspase‐3 (apoptosis execution‐related protein) levels in tumour cells in vivo." (PMID 35522942, 2022). "Furthermore, patients with high levels of NAT10 carried more aggressive tumours and were more likely to develop lymph node metastases." (PMID 35522942, 2022). "Univariate Cox regression survival analysis was performed to identify the risk factors for overall survival, and the results illustrated that NAT10 high group, age (≥ 65), tumour stage (III and IV), HPV-negative status, and recurrent tumour type were risk factors for OS." (PMID 34362389, 2021). "The migration, invasion and cell cycle promotion of the tumour cells may be the mechanisms by which NAT10 promotes tumour progression." (PMID 34362389, 2021). "NAT10 promoted tumour growth by regulating the migration, invasion and cell cycle of tumour cells." (PMID 34362389, 2021). "In addition, NAT10 plays an essential role in regulating the proliferation, migration, invasion and cell cycle of tumour cells, thus promoting tumour growth and progression." (PMID 34362389, 2021). "Consistent with our previous study, NAT10 was expressed in the nuclei of human HCC tumor cells." (PMID 28859621, 2017). "It suggested that NAT10 could exert tumour-promoting effects through multiple pathways." (PMID 40169553, 2025). "However, sh-NAT10-mediated tumor growth inhibition was rescued by OE-FOXD1 administration." (PMID 40999468, 2025). "In addition, inhibitors targeting NAT10 (such as remodelin and panobinostat) have shown significant antitumor activity in vivo and in vitro, suggesting that ac4C modification is expected to become a new molecular target for tumor treatment." (PMID 41316475, 2025). "Furthermore, we verified the roles of NAT10 in GC cells in vivo, and the results showed that overexpression of NAT10 in GC cells significantly promoted tumor growth, as indicated by the larger size and greater weight of these tumors compared with those in the control group." (PMID 39990211, 2025).
tumor (continued). "Therefore, we speculated that NAT10‐modulated lysosomal acidification promotes tumor metastasis through autophagy." (PMID 40729677, 2025). "In summary, NAT10 plays a biologically significant role in the regulation of the tumor cell cycle by influencing the expression of cell cycle‐related genes and the function of cell cycle checkpoints, directly participating in tumor cell proliferation and growth." (PMID 39764566, 2025). "Histopathological analysis (H&E staining) revealed that sh-NAT10-derived xenografts exhibited reduced cell density, abnormal tissue structure, and enlarged intercellular spaces relative to sh-NC controls, reinforcing NAT10 depletion-mediated tumor growth suppression." (PMID 40999468, 2025). "Thus, NAT10 inhibition in GC cells promoted tumor vascular normalization." (PMID 40860183, 2025). "Additionally, NAT10 silencing diminished tumor microvessel density (MVD) of C666-1 NPC xenografts, which could be reversed by FOXD1 reconstitution." (PMID 40999468, 2025). "Moreover, the NAT10 mRNA level was significantly increased in GC tumor tissues." (PMID 39990211, 2025). "Moreover, acetylation of NAT10 influence cell cycle regulation and tumor proliferation." (PMID 39640362, 2024). "Therefore, we speculate that in tumors where CLIC3 is highly expressed, NAT10 will likely act as a tumor suppressor through interacting with CLIC3." (PMID 38182571, 2024). "To further ascertain whether NAT10‐induced proliferation of CCa cells in vitro endows tumor growth ability in vivo, we established a subcutaneous xenograft model in nude mice using SiHa cells with stable silencing of NAT10 (NAT10+/‐ SiHa) tagged with firefly luciferase (‐luc)." (PMID 37818745, 2023). "In addition, as to how NAT10 plays a role in promoting cancer, the following arguments are selected to support the experimental results: NAT10 promotes tumor cell migration and EMT transformation by regulating mRNA N4-acetylcytidine (ac4C) modification pathway." (PMID 36949954, 2023). "In addition, we found that NAT10 is related to tumour immune infiltration." (PMID 36908042, 2023). "Besides, the Wnt/β-catenin pathway which is responsible for tumor progression might be correlated with NAT10, however, their relationship concerning CRC remains largely unknown." (PMID 36522719, 2022). "The in vivo experiments discovered that NAT10 could promote tumor growth and liver/lung metastasis." (PMID 36522719, 2022). "In addition, oxidative phosphorylation is essential for tumour growth and it is necessary to explore whether NAT10 contributes to the metabolism of tumours." (PMID 34362389, 2021). "Moreover, targeting NAT10 alone or in combination with other drugs may be a new strategy for tumour treatment in further investigations." (PMID 34362389, 2021). "Alternatively, THUMPD1 may promote tumor invasion as a NAT10 downstream factor." (PMID 28076326, 2017). "Our syngeneic and carcinogen-induced CRC models demonstrated that Nat10 ablation enhances CD8+ T cell–dependent tumor control, as evidenced by increased cytotoxic CD8+ T cell infiltration, GzmB/IFN-γ production, and tumor regression." (PMID 41542770, 2026). "Meanwhile, 5F8 treatment substantially increased the numbers of tumor-infiltrating CD8+ T cells and effector T cells in Nat10-OE tumors." (PMID 41542770, 2026). "Consistent results were obtained in CT-26 allografts, where Nat10 KO increased the accumulation and activity of CD8+ and CD4+ T cells, which were correlated with tumor growth suppression." (PMID 41542770, 2026). "NAT10 also influences EMT and tumor metastasis through its regulation of cell adhesion molecules, such as E‐cadherin and vimentin." (PMID 39764566, 2025). "The body weight remained consistent across all groups.Flow cytometry analysis revealed that NAT10 knockdown significantly increased CD8 + T cell infiltration and granzyme B levels, indicating enhanced anti-tumor immunity." (PMID 41203621, 2025).